ZNF514 (zinc finger protein 514)
Description:
May be involved in transcriptional regulation.
Synonyms: FLJ14457
Tractability: PROTAC: ubiquitination databases record sites on it.
Gene: Protein-coding gene on chromosome 2 (95,122,087 to 95,165,672, reverse strand). Ensembl gene ENSG00000144026.
Subcellular location: Nucleus
Subcellular location (Human Protein Atlas): Nuclear bodies; Nucleoplasm
Pathways (Reactome):
Gene expression (Transcription): Generic Transcription Pathway
Gene Ontology:
Molecular function: DNA-binding transcription factor activity, RNA polymerase II-specific; RNA polymerase II cis-regulatory region sequence-specific DNA binding
Biological process: regulation of transcription by RNA polymerase II; regulation of DNA-templated transcription
Cellular component: nucleus
Genetic constraint (gnomAD): Loss-of-function variants: 12 observed, 9.77 expected, observed/expected ratio (o/e) 1.23, 90% interval 0.78 to 1.83. That is too few expected variants to judge how well the gene tolerates losing a copy. Missense variants: 467 observed, 480.51 expected, observed/expected ratio (o/e) 0.97, 90% interval 0.9 to 1.05. Synonymous variants: 158 observed, 171.88 expected, observed/expected ratio (o/e) 0.92, 90% interval 0.81 to 1.05.
Homologues: Orthologues: chimpanzee ZNF514 (95% identical), pig ZNF514 (84% identical), dog ZNF514 (82% identical). Paralogues in human: ZFP28 (44% identical), ZNF568 (44% identical), ZNF7 (44% identical), ZNF182 (44% identical), ZNF841 (44% identical), ZNF254 (43% identical), ZNF300 (43% identical), ZNF33B (43% identical), ZNF658 (43% identical), ZFP14 (43% identical), ZNF30 (43% identical), ZNF461 (43% identical), and 164 more.
Diseases named in the same sentence as ZNF514 in open-access papers:
ZNF514 is named in the same sentence as 10 diseases in open-access papers, as found by Europe PMC text mining. Sharing a sentence is not in itself a finding about the gene and the disease. The quoted sentences say what the papers report.
cholangiocarcinoma (1 paper, 2025). A carcinoma that arises from the intrahepatic biliary tree (intrahepatic cholangiocarcinoma) or from the junction, or adjacent to the junction, of the right and left hepatic ducts (hilar cholangiocarcinoma). "Moreover, we found a significant difference in ZNF514 expression between cholangiocarcinoma cancer tissues and normal control tissues, which may be attributed to the differences in the tumor samples." (PMID 40599863, 2025).
colorectal cancer (1 paper, 2025). A primary or metastatic malignant neoplasm that affects the colon or rectum. "Missense mutation of ZNF514 accounted for the largest proportion of all mutation types, with melanoma, colorectal cancer, and pancreatic cancer having the highest occurrence rates of 1.16%, 0.5%, and 0.16%, respectively." (PMID 40599863, 2025).
non-small cell lung carcinoma (1 paper, 2025). A group of at least three distinct histological types of lung cancer, including non-small cell squamous cell carcinoma, adenocarcinoma, and large cell carcinoma. "To date, only three report has been published about ZNF514, which suggests that ZNF514 may play a carcinogenic role in non-small cell lung cancer." (PMID 40599863, 2025).
renal cell carcinoma (1 paper, 2025). "To further investigate the functional role of ZNF514 in renal cell carcinoma (RCC), we conducted EMT and apoptosis experiments on the 786-O (ZNF514 overexpression) and A498 (ZNF514 knockdown) cell lines." (PMID 40599863, 2025).
renal clear cell carcinoma (1 paper, 2025). "The purpose of this study is to investigate the prognostic and immunological roles of ZNF514 in pan-cancer and to confirm its cancer-promoting effect in renal clear cell carcinoma." (PMID 40599863, 2025). "Furthermore, we conducted cellular functional experiments to examine the effects of ZNF514 overexpression or knockdown on renal clear cell carcinoma cell proliferation, migration, and invasion." (PMID 40599863, 2025). "Finally, our molecular biology experiments confirmed the oncogenic effect of ZNF514 in renal clear cell carcinoma." (PMID 40599863, 2025). "Firstly, the expression levels of ZNF514 were determined in human permanent renal tubular epithelial cell HK2 and renal clear cell carcinoma cell lines ACHN, 786-O, Caki-2, OS-RC-2, and A498 by Western blotting." (PMID 40599863, 2025).
cancer (1 paper, 2025). A tumor composed of atypical neoplastic, often pleomorphic cells that invade other tissues. "Further analysis of ZNF514 gene mutation data revealed that ZNF514 protein is infrequently mutated in human cancers." (PMID 40599863, 2025). "We observed that high expression of ZNF514 was associated with a good prognosis in some cancers, while in others, low expression of ZNF514 was correlated with a poor prognosis." (PMID 40599863, 2025). "To investigate the potential association between ZNF514 expression level and prognosis, we conducted a pan-cancer survival analysis with overall survival (OS) and disease free survival (DFS) using the GTEx and Kaplan–Meier survival analysis dataset." (PMID 40599863, 2025). "Additionally, we investigated the possible links between ZNF514 expression and the tumor immune microenvironment and mutation status across various cancers." (PMID 40599863, 2025). "Our study showed that ZNF514 expression was associated with immune cells in most cancer species." (PMID 40599863, 2025). "Moreover, ZNF514 affected prognosis and was associated with the expression of multiple immune checkpoint genes and the abundance of tumor-infiltrating immune cells across multiple types of cancer." (PMID 40599863, 2025). "Further research is needed to verify these findings and determine the potential mechanisms of ZNF514 in the occurrence and progression of cancer." (PMID 40599863, 2025). "Our study indicates that ZNF514 is not only a marker for tumor immune microenvironment changes and poor prognosis but also a promising candidate therapeutic target for cancer treatment." (PMID 40599863, 2025). "To investigate the expression changes of ZNF514 in cancers, we employed TIMER 2.0 and TCGA website to evaluate the mRNA expression level of ZNF514 in tumor tissues and adjacent normal tissues." (PMID 40599863, 2025). "The expression of ZNF514 was elevated in most cancers, including BLCA, CHOL, COAD, ESCA, GBM, KIRC, kidney renal papillary cell carcinoma (KIRP), LIHC, LUAD, LUSC, READ and STAD." (PMID 40599863, 2025). "To detect the expression and prognostic value of ZNF514 in pan-cancers, we utilized The Cancer Genome Atlas (TCGA) or the Genotype-Tissue Expression (GTEx) databases and analyzed the data using the Kaplan-Meier plotter, GEPIA2, cBioPortal, or Xiantao software." (PMID 40599863, 2025). "We also utilized biological experiments to validate the cancer-promoting effect of ZNF514 in ccRCC." (PMID 40599863, 2025). "In order to comprehensively evaluate the expression of ZNF514 in various cancer types, we will conduct a joint analysis based on the Timer2.0 database of the TCGA database and the Xiantao database, respectively analyzing the differences between tumors and normal tissues in each cancer type." (PMID 40599863, 2025). "Our study revealed that ZNF514 may serve as an immunological and prognostic biomarker in multiple human cancers, especially in KIRC, LIHC, LUSC, and COAD." (PMID 40599863, 2025). "Our findings indicated that ZNF514 was significantly overexpressed in 11 types of cancer." (PMID 40599863, 2025). "This may suggest that the level of ZNF514 expression affects tumor heterogeneity at genetic or epigenetic level and changes the immune microenvironment of cancers." (PMID 40599863, 2025). "In addition, these findings also clearly demonstrate that ZNF514 can be utilized as a biomarker to determine the prognosis of various cancers." (PMID 40599863, 2025). "Therefore, we utilized various bioinformatics approaches to conduct a comprehensive pan-cancer analysis of ZNF514." (PMID 40599863, 2025). "Our results showed a significant relationship between ZNF514 and TNM staging in COAD and KIRP, but the prognostic outcome was opposite for these two types of cancer." (PMID 40599863, 2025). "Our analysis also suggested the prognostic value of ZNF514 by analyzing OS, DFS, and ROC in different cancers." (PMID 40599863, 2025).
cancer (continued). "However, previous research on ZNF514 has been limited, and there has been no pan-cancer investigation into the relationship between ZNF514 expression and multiple cancers." (PMID 40599863, 2025). "This suggests that the role of ZNF514 may not be the same in different types of cancer, and the therapeutic emphasis may vary at different cancer stages." (PMID 40599863, 2025). "However, there is a lack of systematic studies on ZNF514 across different types of cancer." (PMID 40599863, 2025). "Zinc Finger Protein 514 (ZNF514) is a member of the ZNF family, and its abnormal expression and prognostic value in human pan-cancer have not yet been described." (PMID 40599863, 2025).
tumor (1 paper, 2025). "While our initial univariate analysis provided evidence for the association between [ZNF514] and tumor proliferation, the subsequent multivariate analysis accounting for age, gender, and tumor stage strengthens the validity of our findings." (PMID 40599863, 2025). "We also used the Tumor Immune Estimation Resource 2.0 (TIMER 2.0) database to investigate the association between ZNF514 expression and immune checkpoint genes and immune infiltration." (PMID 40599863, 2025). "Our analysis revealed that high ZNF514 expression was associated with poor OS in 5 tumor types, such as Adrenocortical carcinoma (ACC) and KIRC." (PMID 40599863, 2025). "As genetic alterations are known to be one of the key factors promoting the occurrence and development of tumors, we utilized the cBioPortal website to analyze the mutation of the ZNF514 gene in all tumor tissue data from TCGA." (PMID 40599863, 2025). "Our study found that ZNF514 expression was elevated in tumor tissues than in normal tissues in most tumor types." (PMID 40599863, 2025). "In contrast, ZNF514 expression in the tumor tissues of BRCA, KICH, THCA and UCEC was significantly decreased." (PMID 40599863, 2025). "In our study, we utilized the Human Protein Atlas (HPA) database to determine the expression of ZNF514 in human normal and tumor tissues." (PMID 40599863, 2025). "This may shed light on the dominant malignant phenotype of ZNF514 in tumor development or metastasis." (PMID 40599863, 2025). "Furthermore, high expression of ZNF514 was associated with poor overall survival (OS) and disease-free survival (DFS) in certain tumor types." (PMID 40599863, 2025). "In contrast, high ZNF514 expression levels were positively associated with better prognosis in GBM.To address the potential confounding effects of clinical variables, we further conducted a multivariate Cox regression analysis using the UALCAN database, including age, gender, and tumor stage." (PMID 40599863, 2025). "However, the mechanisms underlying tumor metastasis remain unclear.ZNF514 has not been widely studied." (PMID 40599863, 2025). "Additionally, we compared ZNF514 expression levels among different clinicopathological stages using the GEPIA database and observed significant associations between ZNF514 mRNA expression and tumor stages in COAD, KIRP, LIHC, LUAD, OV, and TGCT (p < 0.05, Kruskal-Wallis test)." (PMID 40599863, 2025). "Remarkably, the expression levels of ZNF514 exhibited a negative correlation with immune cell infiltration in a majority of tumor types, particularly with regards to dendritic cells and neutrophils." (PMID 40599863, 2025).
ZNF514 also shares sentences with these, for which no sentence is quoted: melanoma (1 paper); nicotine dependence (1); pancreatic cancer (1).